DIAPH3 (diaphanous related formin 3)
Description:
Actin nucleation and elongation factor required for the assembly of F-actin structures, such as actin cables and stress fibers. Required for cytokinesis, stress fiber formation and transcriptional activation of the serum response factor. Binds to GTP-bound form of Rho and to profilin: acts in a Rho-dependent manner to recruit profilin to the membrane, where it promotes actin polymerization. DFR proteins couple Rho and Src tyrosine kinase during signaling and the regulation of actin dynamics. Also acts as an actin nucleation and elongation factor in the nucleus by promoting nuclear actin polymerization inside the nucleus to drive serum-dependent SRF-MRTFA activity.
Synonyms: DRF3; DIAP3; FLJ34705; AN; NSDAN; AUNA1; DIA2; mDia2
Tractability: Small molecule: a structure with a bound ligand is known. Antibody: the Human Protein Atlas places it where antibodies can reach. PROTAC: UniProt records ubiquitination sites on it; ubiquitination databases record sites on it.
Gene: Protein-coding gene on chromosome 13 (59,665,583 to 60,163,928, reverse strand). Ensembl gene ENSG00000139734.
Subcellular location: Cytoplasm; Nucleus
Subcellular location (Human Protein Atlas): Microtubules; Plasma membrane
Pathways (Reactome):
Signal Transduction: CDC42 GTPase cycle; RAC1 GTPase cycle; RAC2 GTPase cycle; RAC3 GTPase cycle; RHO GTPases Activate Formins; RHOA GTPase cycle; RHOB GTPase cycle; RHOC GTPase cycle; RHOD GTPase cycle; RHOF GTPase cycle; RHOG GTPase cycle; RHOJ GTPase cycle; RHOQ GTPase cycle
Gene Ontology:
Molecular function: cadherin binding; actin binding; cytoskeletal protein binding; microtubule binding; protein homodimerization activity; small GTPase binding
Biological process: actin cytoskeleton organization; actin filament polymerization; cytoskeleton organization
Cellular component: cytoplasm; microtubule cytoskeleton; plasma membrane; actin filament; cytosol; nucleus; actin filament bundle; cleavage furrow; ESCRT I complex; microtubule organizing center; ribbon synapse; spindle pole; stereocilia tip-link density
Genetic constraint (gnomAD): Loss-of-function variants: 83 observed, 112.11 expected, observed/expected ratio (o/e) 0.74, 90% interval 0.62 to 0.89. The upper end of that interval is the gene's LOEUF score, 0.89, which puts it in group 3 of 6, group 1 being the genes least tolerant of losing a copy. Missense variants: 1,202 observed, 1,264.4 expected, observed/expected ratio (o/e) 0.95, 90% interval 0.91 to 1. Synonymous variants: 466 observed, 445.75 expected, observed/expected ratio (o/e) 1.05, 90% interval 0.97 to 1.13.
Gene-disease validity (ClinGen):
ClinGen rates the evidence that DIAPH3 causes each of these diseases.
auditory neuropathy (autosomal dominant): Limited. A hearing disorder characterized by impaired transmission of signals through the auditory nerve, resulting in mild to severe hearing loss and poor speech perception.
Homologues: Orthologues: chimpanzee DIAPH3 (99% identical), macaque DIAPH3 (97% identical), rabbit DIAPH3 (91% identical), dog DIAPH3 (91% identical), pig DIAPH3 (85% identical), mouse Diaph3 (83% identical), rat Diaph3 (82% identical), guinea pig DIAPH3 (79% identical), tropical clawed frog DIAPH3 (64% identical), zebrafish diaph3 (58% identical), Caenorhabditis elegans daam-1 (20% identical). Paralogues in human: DIAPH2 (52% identical), DIAPH1 (46% identical), FMNL2 (20% identical), DAAM1 (20% identical), FMNL1 (20% identical), DAAM2 (19% identical), INF2 (19% identical), FMNL3 (19% identical), FHOD3 (16% identical), FMN2 (15% identical), FHOD1 (15% identical), GRID2IP (14% identical), and 6 more.
Diseases named in the same sentence as DIAPH3 in open-access papers:
DIAPH3 is named in the same sentence as 64 diseases in open-access papers, as found by Europe PMC text mining. Sharing a sentence is not in itself a finding about the gene and the disease. The quoted sentences say what the papers report.
breast carcinoma (12 papers, 2012 to 2023). "One in vitro example is DIAPH3 in breast cancer cells, in which cancer-associated fibroblasts (CAFs) regulate tumor cell migration and invasion by secreting protein factors that reduce DIAPH3 protein levels in the tumor cells." (PMID 34685534, 2021). "Loss of DIAPH3, which encodes the mDia2 protein, occurs in primary and metastatic prostate cancer tumors, hepatocarcinoma, breast carcinoma, and in an OvCa progression model." (PMID 24587343, 2014). "In breast cancer, the overexpression of DIAPH3 inhibits the migration and invasion of triple-negative breast cancer by inhibiting the expression of Rho-guanosine-5'-triphosphate." (PMID 36750200, 2023). "DIAPH3 is decreased in breast cancer tissues, and DIAPH3 overexpression inhibits cell migration and invasion of triple-negative breast cancer by inhibiting RhoA-GTP expression." (PMID 35379791, 2022). "DIAPH3 expression level significantly decreases in tissues of patients with breast cancer, and overexpression of DIAPH3 inhibits the migration and invasion of breast cancer cells." (PMID 36589226, 2022). "DIAPH3 deletions are common to several carcinomas and accumulate during cancer progression, as occurs in prostate, hepatocellular, and breast carcinoma." (PMID 34685534, 2021). "Silencing DIAPH3 increases microtubule dynamics and enhances the responsiveness to taxol in prostate DU145 and LNCaP cancer cells, and low levels of DIAPH3 mRNA improve the sensitivity to taxol and other taxanes in prostate and breast cancer cell lines." (PMID 34685534, 2021). "Silencing of DIAPH3 increased the cytotoxic response to taxanes in prostate and breast cancer cell lines." (PMID 26179371, 2015). "Low DIAPH3 expression correlated with improved relapse-free survival in breast cancer patients treated with chemotherapeutic regimens containing taxanes." (PMID 26179371, 2015). "However, Kaplan–Meier survival analysis showed a strong association of high co‐expression of mDia2/DIAPH3 and INHBA with decreased survival of patients with liver, stomach, and breast cancer." (PMID 32150356, 2020). "Similar results were seen using HMEC-RasV12 breast cancer cells in which DIAPH3 was silenced." (PMID 26179371, 2015). "Breast cancer patients, with reduced DIAPH3 expression, were more sensitive to taxol and GBM patients with reduced DIAPH3 expression showed reduced survival times." (PMID 30897774, 2019).
prostate carcinoma (11 papers, 2012 to 2025). A carcinoma that arises from epithelial cells of the prostate gland. "Diaphanous-related formin-3 (DRF3), a signaling protein binding small Rho family GTPases, has been reported to be associated with the formation of MVs when suppressed in prostate cancer cells." (PMID 36435789, 2022). "Here, we show that loss of Diaphanous-related formin-3 (DIAPH3), frequently associated with metastatic breast and prostate cancers, correlates with increased sensitivity to taxanes." (PMID 26179371, 2015). "In contrast, the interacting proteins of DIAPH3 in other tumours, such as prostate cancer and glioblastoma, are tubulin and related microtubule dynamic regulating proteins." (PMID 33345387, 2021). "DIAPH3 downregulation increases the sensitivity of breast and prostate carcinoma cells to taxanes, which are inhibitors of microtubule dynamics." (PMID 34685534, 2021). "The main objective of this study was to identify potential biological functions of microvesicles (MV) produced by prostate cancer cells, in which DIAPH3 was silenced." (PMID 26082317, 2013). "DIAPH3 silencing in prostate cancer and other cell background evokes a transition from a mesenchymal to an amoeboid phenotype, as well as increases tumour cell migration, invasion and metastasis." (PMID 26082317, 2013). "Furthermore, DIAPH3 expression is reduced in invasive prostate cancer and in breast and hepatocarcinoma cells." (PMID 29596520, 2018). "For instance, in prostate cancer cells, deregulation of the Akt pathway, growth factor stimulation (EGF), and loss of the diaphanous related formin 3 (DRF3) leads to the acquisition of a cellular phenotype associated with invasiveness, amoeboid motility, and unique form of neovesiculation." (PMID 22934045, 2012). "Modulation of DIAPH3 expression also regulates the switch between the mesenchymal and ameboid migration modes in human MDA-MB-231 breast and DU145 prostate cancer cells." (PMID 34685534, 2021). "The induced nuclear shape instability mirrored the effects seen upon depletion of lamin A/C or Diaphanous‐related formin 3 (DIAPH3/mDia2), a cytoskeletal protein often absent in metastatic breast and prostate cancer." (PMID 39866838, 2025).
hepatocellular carcinoma (10 papers, 2019 to 2025). A malignant tumor that arises from hepatocytes. "In hepatocellular carcinoma and lung adenocarcinoma, the expression of DIAPH3 was positively correlated with most immune checkpoints." (PMID 36750200, 2023). "In the development of hepatocellular carcinoma, DIAPH3 promotes the growth, migration, and metastasis of hepatocellular carcinoma cells by activating β-catenin/T-cell factor signal transduction." (PMID 36750200, 2023). "Previous studies reported that DIAPH3 is also significantly upregulated in lung adenocarcinoma, pancreatic cancer, and hepatocellular carcinoma." (PMID 37098483, 2023). "DIAPH3 is highly expressed in tissues of patients with pancreatic cancer, lung adenocarcinoma, and hepatocellular carcinoma." (PMID 36589226, 2022). "Upregulation of DIAPH3 expression has also been reported in hepatocellular carcinoma and lung adenocarcinoma." (PMID 35201449, 2021). "In hepatocellular carcinoma, lung adenocarcinoma, and pancreatic cancer, the oncogenic roles played by DIAPH3 expression have all been described." (PMID 34771513, 2021). "Functional in vitro and in vivo experiments have also suggested that DIAPH3 promotes tumorigenesis in hepatocellular carcinoma and lung adenocarcinoma." (PMID 35201449, 2021). "Previous reports have revealed DIAPH3 as a new therapeutic target for hepatocellular carcinoma and lung adenocarcinoma treatment." (PMID 35201449, 2021). "In hepatocellular carcinoma, DIAPH3 expression activated beta-catenin/TCF signaling by binding HSP90 and disrupting the interaction between GSK3 beta and HSP90." (PMID 34771513, 2021). "DIAPH3 can promote tumorigenesis of hepatocellular carcinoma, pancreatic cancer, and lung adenocarcinoma, while suppressing the tumorigenesis of triple-negative breast cancer." (PMID 35201449, 2021). "While only limited information on DIAPH2 is available, DIAPH3, a closely related family member with 57% sequence homology and several common protein binding domains, does promote cell growth and metastasis in hepatocellular carcinoma." (PMID 32276641, 2020). "For example, the SE-driven m6A readers IGF2BP2/3 stabilise DDX21 mRNA to facilitate the progression of acute myeloid leukaemia, and the SE-regulated lncRNA LINC01089 induces alternative splicing of DIAPH3 through m6A modification to drive hepatocellular carcinoma progression." (PMID 41436435, 2025). "Diaphanous related formin 3 (DIAPH3) promotes tumorigenesis in hepatocellular carcinoma and lung adenocarcinoma, suggesting that DIAPH3 may be a target for tumor therapy." (PMID 35201449, 2021). "In addition, DIAPH3 expression is higher in hepatocellular carcinoma and lung adenocarcinoma tissues than in normal control tissues." (PMID 35201449, 2021). "DIAPH3 is important for metastasis of hepatocellular carcinoma cells through stimulation of the beta-catenin/TCF signaling pathway, but this gene may be linked with metastasis of BRCA." (PMID 31311202, 2019).
auditory neuropathy (9 papers, 2013 to 2024). "Previous studies have shown that Diaph3 overexpression causes auditory neuropathy in humans (AUNA1), and mouse models revealed inner hair cell stereocilia defects." (PMID 36400760, 2022). "Overexpression of Diaph3 is associated with auditory neuropathy in human patients and mouse models." (PMID 39322015, 2024). "Mouse models of AUNA1, in which Diaph3 is overexpressed, exhibit auditory neuropathy hearing loss." (PMID 36400760, 2022). "To assess the potential for treating GJB2 and other forms of hereditary hearing loss with ACEMg, we tested the influence of ACEMg on the cochlea and hearing of mouse models for two human mutations: GJB2, the leading cause of childhood deafness, and DIAPH3, a cause of auditory neuropathy." (PMID 26965868, 2016). "Study on the Diaph3 transgenic mice revealed that the mouse overexpressing Diaph3 mimicked the human auditory neuropathy phenotype." (PMID 39322015, 2024). "In cell cycle (CD−M4), Tubb4b was associated with Leber congenital amaurosis, Dnmt1 with DNMT1 methylopathy, and Diaph3 with auditory neuropathy spectrum disorder." (PMID 39684410, 2024). "Transgenic mice that overexpressed Diaph3 displayed altered inner hair cell stereocilia and reduced auditory brainstem responses, resembling the human auditory neuropathy phenotype." (PMID 39322015, 2024). "Expression and activity of Diaph3 is tightly regulated: lack of Diaph3 results in developmental defects and embryonic lethality in mice, while overexpression of Diaph3 causes auditory neuropathy." (PMID 39322015, 2024). "We previously demonstrated that a mutation in the 5′ untranslated region of Diaphanous homolog 3 (DIAPH3) results in 2 to 3-fold overexpression of the gene, leading to a form of delayed onset, progressive human deafness known as AUNA1 (auditory neuropathy, nonsyndromic, autosomal dominant, 1)." (PMID 23441200, 2013). "Interestingly, of 118 deafness genes, several genes have been reported to be associated with auditory neuropathy, a hearing dysfunction characterized by impaired transmission of signal to the auditory nerve by the presynaptic inner hair cells, such as PJVK, NARS2, SLC17A8, DIAPH3 and DIAPH1." (PMID 37062025, 2023).
deafness (9 papers, 2013 to 2024). An inherited or acquired condition characterized by the complete loss of the ability to hear from one or both ears. "Nonsyndromic Autosomal Dominant Auditory Neuropathy 1 (AUNA1) is a form of late-onset progressive deafness resulting from a point mutation in the 5'untranslated region of the Diaphanous Homolog 3 (DIAPH3) gene." (PMID 39442262, 2024). "Auditory neuropathy, non-syndromic, autosomal dominant 1 (AUNA1) is a form of delayed-onset, progressive human deafness resulting from a point mutation in the 5′ untranslated region of the Diaphanous homolog 3 (DIAPH3) gene." (PMID 36769387, 2023). "Auditory neuropathy 1 (AUNA1) is a form of human deafness resulting from a point mutation in the 5′ untranslated region of the Diaphanous homolog 3 (DIAPH3) gene." (PMID 28058271, 2016). "In a mouse model of AUNA1, in which TG mice overexpress WT Diaph3 (encodes Dia2), animals experience progressive deafness and elongated and fused stereocilia selectively in IHCs without HC loss." (PMID 27707755, 2016). "Importantly, pathogenic variants in DIAPH1 and DIAPH3 have been shown to cause deafness." (PMID 36400760, 2022). "To investigate the mechanism of deafness, we generated two lines of transgenic mice overexpressing Diap3, the murine ortholog of DIAPH3, on an FVB/NJ background." (PMID 23441200, 2013).
hearing loss (8 papers, 2016 to 2024). "In humans, defects in two of the three diaphanous genes (DIAPH1 and DIAPH3) have been associated with different types of hearing loss." (PMID 36689403, 2023). "In humans, defects in DIAPH1 and DIAPH3 have been associated with different types of hearing loss." (PMID 35681420, 2022). "Mutations in DIAPH1 and DIAPH3 have been associated with different types of hearing loss." (PMID 35681420, 2022). "Mutations in two formin-related hearing loss genes, DIAPH1 and DIAPH3, are predicted to result in a gain-of-function mechanism." (PMID 38498576, 2024). "The variants in DIAPH3 and USH1C were investigated in the pedigree by Sanger sequencing, and their segregation was not compatible with the segregation of hearing loss in the family." (PMID 33326993, 2021).
pancreatic cancer (7 papers, 2021 to 2023). "Overall, the expression of DIAPH3 is up‐regulated in pancreatic cancer and may be closely associated with the occurrence and development of pancreatic cancer." (PMID 33345387, 2021). "In order to study the molecular mechanism of DIAPH3 in promoting the progression of pancreatic cancer, we screened DIAPH3 interaction proteins by mass spectrometry." (PMID 33345387, 2021). "We further analysed the data in the TCGA database UALCAN and confirmed the up‐regulated expression of DIAPH3 in pancreatic cancer, and this up‐regulation multiple gradually increased along with the progression of pancreatic cancer." (PMID 33345387, 2021). "qPCR result showed that the transcription level of DIAPH3 in several pancreatic cancer cells was higher than that of normal pancreatic cells HPDE, and a similar conclusion was obtained at the protein level." (PMID 33345387, 2021). "In order to further study the function of DIAPH3 in pancreatic cancer cells, we established a stable overexpressing cell line of DIAPH3 in pancreatic cancer cells SW1990 and Miapaca‐2 (hereinafter referred to as Mia Paca‐2)." (PMID 33345387, 2021). "Related databases and clinical tissue sample analysis have found that DIAPH3 is highly expressed in pancreatic cancer and is positively correlated with tumour progression." (PMID 34503532, 2021). "We analysed the interacting proteins of DIAPH3 in pancreatic cancer cell lines with mass spectrometry and performed a GO analysis." (PMID 33345387, 2021). "After knocking down DIAPH3 in pancreatic cancer cells, its proliferation rate was significantly inhibited." (PMID 33345387, 2021). "Further analysis showed that patients with high expressions of DIAPH3 in pancreatic cancer had a shorter survival than patients with low expressions." (PMID 33345387, 2021). "Given that we have discovered the regulatory function of DIAPH3 on the proliferation of pancreatic cancer cells, we further investigated the effect of DIAPH3 on the invasive capacity of pancreatic cancer cells." (PMID 33345387, 2021). "When overexpressing DIAPH3, the non‐anchored growth ability of pancreatic cancer cells SW1990 was significantly up‐regulated." (PMID 33345387, 2021). "Collectively, we regulated the expression level of DIAPH3 in pancreatic cancer cells and found that DIAPH3 could indeed promote the proliferation of pancreatic cancer cells." (PMID 33345387, 2021). "Therefore, it is possible to inhibit the progression of pancreatic cancer through DIAPH3 interference." (PMID 33345387, 2021). "In this study, we first identified DIAPH3 as a highly expressed protein in the tissues of patients with pancreatic cancer, and confirmed that DIAPH3 promoted the proliferation, anchorage‐independent growth and invasion of pancreatic cancer cells using overexpression and interference experiments." (PMID 33345387, 2021). "DIAPH3 also promotes the proliferation and invasion of pancreatic cancer cells." (PMID 34503532, 2021). "According to the database GEPIA (Gene Expression Profiling Interactive Analysis), we found that the DIAPH3 expression was significantly up‐regulated in pancreatic cancer, and the expression level of DIAPH3 in tumour tissues of patients with pancreatic cancer was 6–7 times that of normal tissue." (PMID 33345387, 2021). "We used the cell lines established in pancreatic cancer cells to conduct our study and found that DIAPH3 could regulate the invasive capacity of pancreatic cancer cells." (PMID 33345387, 2021). "Our results indicated that DIAPH3 promoted the malignant phenotype of pancreatic cancer cells." (PMID 33345387, 2021). "Collectively, our observations indicate DIAPH3 could promote pancreatic cancer progression by activating selenoprotein TrxR1‐mediated antioxidant effects." (PMID 33345387, 2021).